EGFR (epidermal growth factor receptor)
Diseases named in the same sentence as EGFR in open-access papers (continued):
Sharing a sentence is not in itself a finding about the gene and the disease.
cancer (continued). "Epidermal growth factor receptor (EGFR) is upregulated in various cancer including pancreatic." (PMID 24040120, 2013). "Several emerging biomarkers that could identify the subset of erlotinib-sensitive EGFR wild-type cancers are undergoing clinical testing." (PMID 24100924, 2013). "As each of these cancer types exhibits dependency on components of the EGFR pathway at similar frequencies, we anticipated that through combining them we might uncover a common genetic predisposition." (PMID 24152305, 2013). "Taken together, our data suggested that cellular dependence on EGFR, which can be predicted by basal Mig6/EGFR ratio, underlie the response of cancer cells to erlotinib rather than the absolute expression level of Mig6." (PMID 23935914, 2013). "Generally, gefitinib-responsive lung cancers—but not nonresponsive cancers—harbor mutations within the EGFR kinase domain." (PMID 23748900, 2013). "Overall, our findings suggest that TACC3 plays an important role in EGF-mediated EMT and may serve as an attractive therapeutic target for human cancers driven by EGF/EGFR signaling pathways." (PMID 23936413, 2013). "Furthermore, a clinical study has shown that cancer patients with an overexpression of EGFR usually have a poor prognosis." (PMID 24273605, 2013). "Indeed, these authors had reported, in colon MSI cancer cell lines, that a deletion within the EGFR polyA tract increases in vitro the EGFR mRNA stability." (PMID 23565769, 2013). "Alterations in the structure, expression, and signaling of EGFR may be involved in the development and metastasis of a wide variety of cancers." (PMID 23990977, 2013). "A population of putative cancer stem cells with enhanced sphere-forming ability, reduced sensitivity to radiation and conventional chemotherapy, and demonstrated resistance to gefitinib (EGFR-targeting drug) has also been demonstrated in FOSCC." (PMID 23970998, 2013). "In addition, when sensitive cancer cells are transformed to a lower phospho-EGFR phenotype, as is seen in an induced EMT-like transition, erlotinib resistance occurs." (PMID 23935914, 2013). "Results showed that simultaneous targeting of EGFR and mTOR inhibits the growth of cancer cells." (PMID 23861714, 2013). "There is also interplay between IGFBP3 and EGFR in cancer cells." (PMID 24019942, 2013). "Another cancer-specific EGFR isoform, de4 EGFR, is also recognized by mAb CH12." (PMID 24285959, 2013). "Finally, it is noteworthy that aberrant activations of EGFR signalling are frequently observed in many types of advanced stage cancers and bone metastases." (PMID 23844832, 2013). "Furthermore, as EGFR and EGFRvIII are substantially expressed by the cancer cells in GBM, these receptors are amendable for targeted therapy." (PMID 24175095, 2013). "EGFR-TKI causes different adverse events from other anti-cancer agents, though molecular targeted anti-cancer drug was expected to be less harm than the other cytotoxic anti-cancer drugs." (PMID 23420789, 2013). "Although EGFR inhibitors are currently being used clinically for the treatment of cancer, additional studies are necessary to determine whether abrogation of EGFR signaling is a potential strategy for the treatment of cardiovascular disease." (PMID 24132149, 2013). "Furthermore, it would be of extreme benefit to the fight against cancer if these results were comparable with the outcomes of anti-EGFR monoclonal antibody and KRAS status in CRC." (PMID 24283603, 2013). "FUT1 may serve as a new molecular target for HER2-overexpressing human cancers with activated EGFR signaling." (PMID 23128605, 2013). "EGFR is highly expressed in cancer cells in more than 40% of GBM cases, and the mutated form of EGFR, EGFRvIII, is additionally expressed in more than 40% of GBM cases expressing EGFR, clearly indicating that EGFR could play a role in GBM pathogenesis." (PMID 24175095, 2013).
cancer (continued). "This ß1 integrin-mediated EGFR recruitment and transactivation has been often reported in cancer cells and suggested to be important for a concerted regulation of invasion but, here, we show for the first time that this can occur inside ß1 integrin promoted invadopodia." (PMID 24086451, 2013). "Elevated levels of Src and EGFR are often found in a variety of cancer cells." (PMID 23702846, 2013). "In addition, Egfr (epidermal growth factor receptor), Gadd45A (growth arrest and DNA-damage-inducible protein) and Id1 (inhibitor of differentiation) are well known to function in cancer pathways." (PMID 23922661, 2013). "EGFR-TKIs are thought to partially affect these cancer related pro-inflammatory cytokine networks." (PMID 23566546, 2013). "EGFR expression was increased in all cancer tissues compared to normal tissues." (PMID 24321281, 2013). "Activation or overexpression of EGFR is a common feature in various human cancers." (PMID 23383347, 2013). "However overexpression of other growth factor receptors such as EGFR and c-Met is frequently reported for this subset of cancers." (PMID 23762292, 2013). "The median time elapsed between cancer diagnoses and receiving EGFR testing results was 21 days." (PMID 23468851, 2013). "Nevertheless, the daily dosing regimen provided peak drug levels sufficient to inhibit EGFR activation as established in a xenograft model of cancer, and also allowed us to observe a pharmacodynamic effect in spinal cord in the present study (reduction in pEGFR staining)." (PMID 23638043, 2013). "Cancer-derived EVs contain intact oncogenes (e.g. EGFR or Ras), and they may be taken up by other cells, whereupon they induce transformation-like changes." (PMID 26082317, 2013). "The eight IA genes we identified are associated with cellular cytoskeleton, cell invasion and oncogenetic signaling, including the well-known cancer driver EGFR, and FAK-Src signaling (ITGA3, MYLK); ITGA3 (integrin, alpha 3) mediates cell survival and invasion through FAK-Src signaling." (PMID 23590835, 2013). "Thus, these materials designed for the Y845-containing region of EGFR are useful tools to investigate the cellular functions regulated by Y845, with a potential for further development as therapeutic reagents for cancer and other diseases." (PMID 23702846, 2013). "We also compare the cell growth promoting effect of both peptides in order to evaluate the potential application of EGFt as EGFR blocker for cancer therapy as well as a potential delivery agent of radio-nuclei conjugates or toxins to cancer cells overexpressing EGFR." (PMID 23935985, 2013). "Therefore the EGFR network can drive the cancer cell phenotype subject to a variety of positive and negative regulatory mechanisms acting at the level of the receptor." (PMID 23825523, 2013). "However, excessive EGFR signaling is observed in many human cancers of epithelial origin, which is involved in neoplastic transformation, including initiation and progression of cancers." (PMID 23457600, 2013). "Hence, the concurrent inhibition of IGF-IR and EGFR provides a logical rationale for combining anti-IGF-IR and anti-EGFR strategies in the treatment of cancer." (PMID 23921573, 2013). "However, limited therapeutic benefits to cancer patients have been derived from EGFR-targeted therapies." (PMID 24349829, 2013). "Cancer cells with EGFR overexpression could be erlotinib-resistant due to reduced dependence on EGFR signaling as predicted by higher Mig6 expression levels." (PMID 23935914, 2013). "Similarly, IGF1R inhibition in combination with EGFR inhibition in EGFR over-expressing cancer cells or IGF1R inhibition in combination with HER2 inhibition in HER2 positive cancer cells have also shown improved results over the use of single agents only." (PMID 24244833, 2013). "Various untransformed and cancer-derived cell types express both AR and EGFR." (PMID 24130806, 2013).
cancer (continued). "Cancer stem cells have been shown to produce cytokines, chemokines, angiogenic factors, and possess up-regulated signaling cascades essential for cancer metastasis, including hedgehog, epidermal growth factor receptor, NOTCH, and Bmi-1." (PMID 22592563, 2013). "Further investigations may be required to determine if the use of the EGFR inhibitors could affect the bone density in cancer patients, leading to pathological fractures." (PMID 23844832, 2013). "The generation of a population of cancer cells with stem-cell properties might provide another possible reason of resistance to EGFR inhibitor." (PMID 23819113, 2013). "Cancer cell resistance to EGFR antagonists could be due to several reasons, such as genetic alterations, which enable them to have an intrinsic resistance to anticancer drugs." (PMID 23409107, 2013). "While some die under the sustained stress environment, others may acquire growth advantage, for example, overexpression of EGFR due to polysomy of chromosome 7 may maintain basal glucose uptake and support cancer cells survival in the low glucose medium." (PMID 23675453, 2013). "These could also explain why EGFR antibody treatment is initially effective to most KRAS wild-type cancer patients and then losts its efficiency as therapy continues." (PMID 23874486, 2013). "Thus, identifying additional agents that can target EGFR through novel strategies is an important goal in the treatment of cancer." (PMID 23935985, 2013). "EGF stimulates cancer growth through the EGFR receptor (EGFR) pathway." (PMID 23592411, 2013). "Detailed molecular understanding of the EGFR kinase domain led to development of specific inhibitors, Gefitinib, Erlotinib, Herceptin, Cetuximab, currently used to treat breast, lung, ovarian, prostate, head-and-neck and other cancers." (PMID 23391100, 2013). "EGFR is a transmembrane tyrosine kinase receptor overexpressed in a wide range of cancers including breast, ovarian, bladder, head and neck, glioma, pancreatic, kidney, lung and prostate, making it an attractive target for both therapeutic and diagnostic applications." (PMID 24564841, 2013). "KIT amplification, auto-phosphorylation of EGFR, and aberrant expression of other receptor tyrosine kinases have also been postulated by in vitro experiments to cause resistance to crizotinib in ALK-rearranged cancer cells." (PMID 24279718, 2013). "Some patients with EGFR wild-type cancers also benefit from erlotinib treatment." (PMID 24100924, 2013). "Anti-epidermal growth factor receptor (EGFR) monoclonal antibodies (MoAbs) cetuximab and panitumumab have emerged as an effective targeted therapy in the treatment of cancer patients, but the overall incidence and risk of fatal adverse events (FAEs) associated with these agents is still unclear." (PMID 24312376, 2013). "EGFRvIII is a commonly found mutant of EGFR and exclusively expressed in a wide range of cancers." (PMID 23656794, 2013). "There are some alternative approaches to evaluate the EGFR Y845-dependent cancer cell conditions." (PMID 23702846, 2013). "Gefitinib is an aniline quinazoline compound that may be used to promote apoptosis, limit angiogenesis and restrict differentiated proliferation or migration of cancer cells via the potent inhibition of EGFR tyrosine kinase." (PMID 24649233, 2013). "Thereby, EGFR has been tremendously studied for its role in cancer development." (PMID 23967242, 2013). "Epidermal growth factor receptor (EGFR) is overexpressed in many types of cancer cells." (PMID 23774942, 2013). "This aberrant activity of EGFR or other ErbB family members activate a number of down stream targets and may contribute to the constitutive STAT3Tyr705 phosphorylation found in cancer cells." (PMID 24025152, 2013). "Notably, GST is known to inhibit tyrosine kinase activity of EGFR leading to induction of apoptosis in various cancer models." (PMID 24205354, 2013).
cancer (continued). "Our results open the horizon for the development of more efficient inhibition tests for EGFR and in general for tyrosine kinase receptors via expression in E. coli, which might allow an easier selection of cancer antagonists targeting these receptors." (PMID 24187524, 2013). "EGFR is a promising target for combination with radiotherapy in many cancer types." (PMID 23951036, 2013). "Accordingly, a combination of IL-6 pathway blocker and EGFR-TKI may show more favorable effects in cancer patients." (PMID 23592411, 2013). "Since Mig6 functions as a negative regulator of EGFR activity, PI3K-AKT-mediated upregulation of Mig6 could negatively regulate signal input from EGFR once a cancer cell senses adequate growth and survival signals from alternative sources." (PMID 23935914, 2013). "In addition, these findings suggested that a cancer cell line that harbors a concurrent ALK rearrangement and an EGFR mutation would be expected to be resistant to both single agent ALK and EGFR inhibitors." (PMID 23714228, 2013). "Cancerous cells overexpress a number of proteins, including growth factor receptors, such as EGFR." (PMID 23432803, 2013). "Thus, adding an EGFR TKI or mAb to inhibit EGFR activation induced by irradiation become a very sound strategy in enhancing the radiocurability of EGFR over-expressing cancers." (PMID 24252457, 2013). "EGFR and its family members are the major contributors of a complex signaling cascade that modulates proliferation, anti-apoptosis, differentiation, adhesion, migration and survival of cancer cells." (PMID 24312376, 2013). "However, the fact that clathrin independent regulation of EGFR appears to be important in other cells suggests that EGFR can also utilize other pathways of endocytosis in cancer." (PMID 23472148, 2013). "As is the case for cancer, the EGFR is important for the normal epidermis." (PMID 23383079, 2013). "Understanding how germline genetic variation influences the EGFR pathway in cancer may aid in prediction of patient responses to targeted therapeutics." (PMID 24152305, 2013). "The activation of HIF-2α in cancer cells increases the expression of EGFR in response to hypoxia." (PMID 24376819, 2013). "Moreover, alterations of the epidermal growth factor receptor (EGFR) gene are common in some forms of cancer and the most frequent is a deletion of exons 2–7." (PMID 23667810, 2013). "EGFR signaling is crucial for enhanced proliferation and survival of cancer cells." (PMID 23555785, 2013). "In this study, we demonstrated that 3,4-dihydroxyphenyl acetic acid and (+)-epoxydon from marine algae reduced expression of the mitogenic signaling cascade and EGFR activation, leading to apoptosis in HeLa cells because EGFR has been indicated to be an important target in cancer therapy." (PMID 23706036, 2013). "Limited studies have examined the role of EGFR and its ligands in angiogenesis in the normal vasculature, whereas a large body of literature in the cancer field documents a link between EGFR and vascular endothelial growth factor (VEGF), a well-known initiator of angiogenesis." (PMID 24132149, 2013). "Emerging findings suggest that oncogenes, such as epidermal growth factor receptor (EGFR) or its mutant, EGFR variant III (EGFRvIII), hypoxia-inducible factor (HIF)-1α and K-ras may trigger the release of EVs from cancer cells." (PMID 24009895, 2013). "Interestingly, PKM2 recently was found playing a non-metabolic role in tumorigenicity by regulating beta-catenin transactivation upon EGFR activation in cancer cells." (PMID 24318446, 2013). "In a large cancer center in Korea, the proportion of EGFR testing increased from 2007 through 2010." (PMID 23468851, 2013). "In addition, the overexpression of TGFα and EGFR by many carcinomas correlates with the development of cancer metastasis, resistance to chemotherapy and poor prognosis." (PMID 23986907, 2013).
cancer (continued). "Furthermore, we found a direct relationship between the SBR and the number of EGFR positive carcinoma cells in a heterogeneous culture containing both COLO205 and IEC6 cells." (PMID 23857061, 2013). "We have previously reported that inhibition of EGFR signalling axis and activation of PPARγ axis are both effective in significantly inhibiting proliferation of human carcinoma cells through different pathways, in part converging to PI3K/Akt, cyclin D1, and cyclin-dependent kinase inhibitors." (PMID 23409107, 2013). "However, the over-expression of EGF was an aggressive biological behavior, as increased levels of EGF/EGFR were detected in innumerable types of carcinomas." (PMID 23825635, 2013). "Epidermal growth factor receptor (EGFR, ErbB, or HER) family members are essential regulators of cell growth, development and normal adult cellular physiology and are implicated in many abnormal physiological conditions such as cancers." (PMID 23284778, 2012). "Interestingly, we also found that YM155 downregulated the epidermal growth factor receptor (EGFR) in various cancer cell lines and induced the EGFR phosphorylation and ubiquitination of EGFR in PANC-1 cells." (PMID 22723871, 2012). "Aberrant epidermal growth factor receptor (EGFR) activation is involved in cancer progression." (PMID 22457794, 2012). "We hypothesized that the structural role of the JXM region could be mimicked by peptides encoding a JXM amino acid sequence, which could interfere with EGFR signaling and consequently could have anti-cancer activity." (PMID 23166750, 2012). "Afatinib (BIBW 2992, Boehringer Ingelheim GmbH), an irreversible dual inhibitor of EGFR and HER2 kinases, retains some activity in tumors with T790M mutations although at doses that are a log higher than what is needed for cancers with only a sensitizing mutation." (PMID 22436374, 2012). "Aberrant EGFR activation, mediated primarily through changes in gene amplification and autocrine stimulation, appears to be a key factor in tumorigenesis, as well as an essential driving force for the aggressive growth behavior of cancer cells." (PMID 22919383, 2012). "If this hypothesis were correct, then constitutive activation of EGFR in normal stem cells or progenitor cells could ostensibly lead to cancer." (PMID 22384257, 2012). "Drugs targeting EGFR have shown promising clinical results for several cancer types." (PMID 23166750, 2012). "Unlike different cancer types where EGFR-positive disease is associated with an adverse prognostic value, EGFR positivity is not prognostic of patient outcome in metastatic gastric or GE cancer." (PMID 23153332, 2012). "Similarly, OS advantage for sorafenib plus erlotinib compared with erlotinib alone was also suggested among patients with EGFR FISH–negative cancers (median OS: 10.55 months for sorafenib plus erlotinib vs 4.60months for erlotinib; one-sided P = 0.064)." (PMID 22916093, 2012). "In addition, radiation can enhance EGFR expression, which, in turn, increases radioresistance of cancer cells." (PMID 22229096, 2012). "Epidermal growth factor receptor (EGFR) inhibitors are widely used in the treatment of cancer." (PMID 22761877, 2012). "This also applies to many other cancer types such as colon cancer, ovarian cancer and bladder cancer, and small molecular weight chemotherapeutic agents or antibodies that target EGFR and HER2 and inhibit their activity have been proven to be clinically effective in overexpressing cancers." (PMID 22240796, 2012). "Proteins composed of a bispecific scFv directed against both the feline spike protein and the EGFR could mediate FIPV and fMHV infection of EGFR-expressing human cancer cells, with subsequent syncytia formation typical of a productive coronavirus infection." (PMID 22312365, 2012).